KL (klotho)
Diseases named in the same sentence as KL in open-access papers (continued):
Sharing a sentence is not in itself a finding about the gene and the disease.
retinopathy (5 papers, 2020 to 2025). "They revealed that the Klotho gene variant was less common in the retinopathy group compared to uncomplicated diabetic patients." (PMID 38374169, 2024). "The authors concluded that reducing circulating Klotho levels by half, increased the risk of retinopathy progression by 44%22." (PMID 38374169, 2024). "Our results suggest that a halving of circulating Klotho levels increases the risk of retinopathy progression by 44%." (PMID 33225726, 2020). "In multivariable logistic regression analyses, baseline log Klotho levels was the only variable independently associated with reduced risk of progression of retinopathy (OR 0.067, 95% CI 0.006–0.693, p = 0.015)." (PMID 33225726, 2020). "In multivariable logistic regression analyses, baseline Klotho level was the only variable independently associated with reduced risk of progression of retinopathy." (PMID 33225726, 2020). "This study aimed to provide an in-depth analysis of retinopathy caused by Klotho mutation." (PMID 40373038, 2025). "Further larger studies are required to determine the effect of Klotho levels on these distinct retinopathy endpoints." (PMID 33225726, 2020). "Our study was also not designed to explain the potential pathophysiology between circulating Klotho level perturbations and progression of retinopathy." (PMID 33225726, 2020). "The results showed that compared with healthy controls, serum Klotho levels in diabetic patients, especially those with DR, decreased significantly, and the degree of decline was negatively correlated with the severity of retinopathy." (PMID 41438297, 2025). "The patients who had lower levels of Klotho were more likely to progress to retinopathy." (PMID 38374169, 2024). "This study was clinical in nature and did not investigate the underlying mechanism of the Klotho/FGF23 axis on retinopathy progression." (PMID 38374169, 2024). "Absence of this common retinal change may limit the use of Klotho mutant mice to reflect the typical retinopathy associated with AD." (PMID 40373038, 2025). "People with progression of retinopathy had lower levels of serum Klotho as compared to those without (median (interquartile range) 226.9 (171.1–394.0) vs 484.5 (221.8–709.9) pg/ml, p = 0.001)." (PMID 33225726, 2020). "We also measured several emerging markers of retinopathy risk such as VCAM-1, ox-LDL, hsCRP in a sub-group of patients and other hormones associated with Klotho such as FGF-23 and vitamin D which were not significantly different between groups." (PMID 33225726, 2020). "However, we observed the novel finding of lower levels of circulating Klotho (median (IQR) 226.9 (171.1–394.0) vs 484.5 (221.8–709.9) pg/ml, p = 0.001) in patients with progression of retinopathy as compared to those without." (PMID 33225726, 2020).
inflammation (4 papers, 2021 to 2025). Aberrant reaction of the microcirculation characterized by movement of fluid and leukocytes from the blood into extravascular tissues. "Additionally, CS‐induced KL+/− mice demonstrated that KL could enhance lung inflammation and the senescence of club cells." (PMID 39930762, 2025).
genetic disease (3 papers, 2021 to 2024). "It is notable that patients with genetic diseases such as tumoral calcinosis, which is associated with missense mutation in Klotho, suffer severe craniofacial abnormalties, underscoring the essential role of Klotho in craniofacial bone development." (PMID 35538062, 2022). "Tumoral calcinosis is an extremely rare genetic disease caused by mutations in three genes, GALNT3, FGF23, and KL, which disrupt phosphorus metabolism." (PMID 38792634, 2024).
vascular disorder (3 papers, 2005 to 2023). A general term used to describe any disease affecting blood vessels]. "In CKD, Klotho deficiency appears in the early stages and gradually decreases with the progression of the disease, also being related to the appearance of vascular disorders, including arterial stiffness." (PMID 37686263, 2023). "We tested not only the hypothesis that alleles of LMNA or KLOTHO would be associated with premature CAD (a population enriched for inherited contributions), but also pre-specified that such premature vasculopathy might be associated with an excess of homozygosity at the LMNA locus." (PMID 16262891, 2005). "In our setting, this evidence suggests that Klotho does not relate to (and may not be an actual player in) the development of vascular disorders and events." (PMID 28076518, 2016).
benign tumors (2 papers, 2020 to 2022). "However, in our investigation, ischaemic heart injury and reduced mechanical function of the heart were related to the high content of Klotho in coronary effluents." (PMID 32319182, 2020).
psychiatric diseases (2 papers, 2021 to 2026). "Klotho has started to be studied as a new potential biomarker in psychiatric diseases, and it is thus important to examine its relationship with neurocognitive tests." (PMID 34763683, 2021). "The role of Klotho in psychiatric disorders has not yet been adequately studied." (PMID 34763683, 2021).
central nervous system disorder (1 paper, 2020). A disease involving the central nervous system. "Central nervous system disorders, neurodegenerative in nature, and especially those affecting the myelin sheath, represent worthy targets for advancing therapies that act upon Klotho pathways." (PMID 32257625, 2020).
connective tissue diseases (1 paper, 2018). "Therefore, in the settings of connective tissue diseases and perhaps also other inflammatory states, the α-Klotho level may be determined by the balance between reduced Klotho synthesis caused by VD deficiency and inflammation and direct activity of FGF23." (PMID 30562918, 2018).
endocrine diseases (1 paper, 2024). "The klotho protein, a multifunctional protein, has been shown to be associated with a wide range of endocrine diseases and has been linked to thyroid tumourigenesis." (PMID 38696398, 2024).
female reproductive diseases (1 paper, 2023). "Recently, klotho has gained broad attention in female reproductive diseases, with various physiological and pathological role of Klotho in the hypothalamus-pituitary-ovary axis." (PMID 37522130, 2023).
hematological malignancies (1 paper, 2017). "In these malignancies, Klotho was elucidated to be a modulator of several signaling pathways, including the FGF signaling, insulin-like growth factor-1 receptor (IGF-1R), and Wnt pathways, which are also involved in the pathogenesis of hematological malignancies." (PMID 28153033, 2017). "However, the role of Klotho in hematological malignancies has not been reported." (PMID 28153033, 2017).
respiratory diseases (1 paper, 2024). "Klotho plays an important role in respiratory system diseases and may be a potential therapeutic target for airway diseases." (PMID 38287280, 2024). "Therefore, Klotho protein may offer a novel therapeutic strategy for the prevention and treatment of respiratory diseases." (PMID 38287280, 2024). "A large number of studies have confirmed that klotho play an important role in respiratory diseases, while FeNO can reflect the level of airway inflammation, but there is no report on the relationship between klotho protein level and FeNO at present." (PMID 38287280, 2024).
KL also shares sentences with these, for which no sentence is quoted: hypertrophy (7 papers); Atrophy (4); idiopathic pulmonary fibrosis (4); inflammatory bowel disease (4); Calcium-Phosphorus Metabolic Disorder (3); glioblastoma (3); Hypocalcemia (3); pulmonary disease (3); rickets (3); vascular dementia (3); acute myocardial infarction (2); bronchopulmonary dysplasia (2); cardiac arrhythmia (2); cholangiocarcinoma (2); cystic fibrosis (2); dialysis (2); endometrial carcinoma (2); essential hypertension (2); Glomerular sclerosis (2); Hearing impairment (2); hematological cancers (2); lung obstructive disease (2); mineral metabolism disease (2); muscular dystrophy (2); nephrolithiasis (2); nephrotic syndrome (2); prediabetes (2); Ventricular hypertrophy (2); Acute tubulointerstitial nephritis (1); adenocarcinoma (1).
A further 80 diseases each share a sentence with KL in 1 paper.